IL6 (interleukin 6)
Diseases named in the same sentence as IL6 in open-access papers (continued):
Sharing a sentence is not in itself a finding about the gene and the disease.
tumor (continued). "Patients in the IRE group had elevated serum levels of immunogenic cytokines, including IL-2, IL-6, and TNF-α, which were related to anti-tumor immunity." (PMID 36428767, 2022). "The activity of JAK and STAT3 is enhanced due to the overexpression of pro-inflammatory cytokines like IL-6, IL-10, IL-11, and TGF-α to regulate the tumor micro-environment, which eventually create the oncogenic conditions to inhibit apoptosis." (PMID 35401182, 2022). "Adipocyte-derived leptin and IL-6 play key roles in the activation of the Jak/STAT and PI3K/Akt/mTOR pathways, which are frequently dysregulated in tumor pathogenesis." (PMID 35805003, 2022). "IL-6, IL-8, TGF-β, NFκ and TNF-α are some of the elements shown to play a role in the tumor-induced inflammatory environment." (PMID 35659296, 2022). "In contrast to the effect of celecoxib on tumor lysate induced DCs, we here show that celecoxib reduced TLR-induced production of IL-10, IL-12, TNF-α, and IL-6." (PMID 36227963, 2022). "Caerin 1.1/1.9-treated TC-1 cells secrete proinflammatory cytokines, such as TNF-α, IL-1β, IL-6, and MCP-1, that promote immune cell trafficking to the tumor site." (PMID 35445137, 2022). "Molecules such as TNF-α, IL-1β, IL-6, IL-21, TGF-β, and IL-23 which are secreted by the immune and tumor cells, accumulated in the TME, can play a vital role in inducing Th17 development." (PMID 35248028, 2022). "Numerous studies have found that the IL6-JAK-STAT3 signaling pathway was activated abnormally in a variety of tumor tissues, which has an immense influence on tumor progression." (PMID 36072012, 2022). "In the tumorigenesis process, tumor cells promote tumor spread and metastasis through inflammation by releasing TNF-α, IL-6, IL-1, and interferon factors, which in turn stimulate tumor cell growth, motility, and invasion." (PMID 36233009, 2022). "The IL-6 target genes MET, IGF1, MMP3, CEACAM1, MMP1 and WNT5A were upregulated, which enabled the tumour cells to become invasive." (PMID 35022523, 2022). "Particularly, by increasing the expression of IL-6, sevoflurane activated the signaling pathway of IL-6/JAK/STAT3, induced the aggregation of CD11b bone marrow stromal cells in lung tissues, and promoted the metastasis of tumor cells to the lung." (PMID 35966857, 2022). "The IL-6-high group showed higher female ratio, AST levels, tumor markers, Child–Pugh score, and vascular invasion ratio." (PMID 35205631, 2022). "IL‐6 is expressed at the high levels in the TME by immune cells, tumor cells, and stromal cells and acts as both pro‐ and anti‐inflammatory cytokine." (PMID 35356799, 2022). "Previous studies have demonstrated that multiple immunosuppressive cytokines, such as IL-6, IL-10 and TGF-β promote the maturation and recruitment of immunosuppressive cells and impair the anti-tumor functions of NK cells and CD8+ T cells." (PMID 35656301, 2022). "Compared with the direct involvement of IL6 in the process of bone destruction, TGFB1 mainly plays a role in the process of tumor bone metastasis." (PMID 35872837, 2022). "These cytokines (IL-1, IL-6, TNF, IL-17, etc.)have been proved to promote tumor cell proliferation, angiogenesis and metastasis." (PMID 36104733, 2022). "The carrier-free UA NPs exhibited the improved immunostimulatory activity of TNF-α, IL-6, and IFN-β in vitro and inhibited tumor growth with significant activation of CD4+ T cells in vivo, revealing their great potential for cancer immunotherapy." (PMID 36015215, 2022). "Literature has shown that IL-6 can inhibit the immune-killing ability of NK cells to tumors by activating the JAK/STAT3 pathway, thereby promoting tumor progression." (PMID 36384635, 2022). "For example, PHLDA1 was positively correlated with the infiltration levels of a variety of immunocompetent tumor-infiltrating cells, including Act CD4, CD56dim, and Act DC and 23 types of immune promoters, including IL6, NT5E, and TNFSF9." (PMID 36142223, 2022).
tumor (continued). "IL-6 is known to transmit signals through several signaling pathways, including JAK/STAT, RAS/MAPK, PI3K/Akt, and NF-κB, to drive tumor progression." (PMID 35565306, 2022). "Both IL-6 and TNF-α were also increased in the tumour-bearing SID mice compared to the tumour-bearing mice without intercurrent surgery." (PMID 36010845, 2022). "0.5 × 106 Panc47 FAK-wt CTL shRNA, FAK-wt IL6 shRNA1 or FAK-wt IL6 shRNA2 cells were implanted into the pancreas of C57BL/6 mice, mice sacrificed 2 weeks later, and tumours processed for analysis using flow cytometry." (PMID 36138073, 2022). "In one study, lower concentrations of ellagic acid decreased IL-1β, IL-6, IL-1Ra, and IL-10 production by PBMC incubated with a tumor cell line (HT-29), whereas higher concentrations inhibited the production of all cytokines examined, except IFN-γ." (PMID 35745713, 2022). "Cytokines such as IL-6, IL-10, and TGF-β produced by tumor cells in the TME hinder the activation of NK cells." (PMID 36686745, 2022). "In another study, IL-10 as an anti-inflammatory cytokine was significantly increased, whereas Tumor necrosis factors TNF-α and IL-6 decreased following calorie restriction." (PMID 36364892, 2022). "Based on RNA sequencing analysis of the tumor, we observed the signaling pathway most affected by NTP was the IL‐6/JAK/STAT3 pathway, which was downregulated after treatment." (PMID 36176603, 2022). "Further, nuclear transcription factor-κB (NF-κB), a key factor in inflammation and tumor cells, induces TNF-α and IL-6 chemotactic leukocytes to infiltrate the inflammation site." (PMID 36406359, 2022). "Among them, we paid special attention to multiple immune pathways, including the inflammatory response, interferon gamma response, TNF-a signaling pathway and IL-6/JAK/STAT3 signaling, all of which had been shown to be closely related to tumor development." (PMID 35991547, 2022). "Metabolic imbalances in the skeletal muscle are mediated by tumour-derived pro-inflammatory cytokines, such as tumour necrosis factor-α (TNF-α), interleukin-1 (IL-1), IL-6, and transforming growth factor β1 (TGFβ1)." (PMID 35406121, 2022). "To further validate the relevance of IL-6/STAT3 axis in the control of SMG1 expression and thus of the NMD activity, we used different tumor-cells expressing the NMD luciferase reporter plasmid cultured in the presence of hyper-IL6." (PMID 36443756, 2022). "The consequent overproduction of key cytokines (IL-1β, IL-6, and TNF-α) played an important role in the exacerbated tumor burden in the AOM/DSS + Abx + Akk group." (PMID 36312913, 2022). "TGFB1, IL-6 and CXCL12 played an important role in the cell-cell communication between residual tumor cells and CAFs." (PMID 35784460, 2022). "The protein levels of STAT3 and IL-6, the activator of STAT3 pathway, were significantly higher in the tissues adjacent to tumor from M2- and M3-injected mice, compared to their expression in the livers of WT counterpart-injected mice." (PMID 35805045, 2022). "Interleukin 6 (IL-6) is produced by a variety of cell types in the tumor microenvironment (TME), including tumor-infiltrating immune cells, stromal cells and tumor cells themselves." (PMID 35223512, 2022). "CAFs’ secrete cytokines or chemokines to interfere with tumor-retarding T cells functions, such as PGE2, indoleamine 2,3-dioxygenase, CXCL12, and IL-6." (PMID 35327514, 2022). "In the tumor environment, IL-6 can activate STAT3 signaling in both cancer cells and tumor-infiltrating immune cells, including macrophages, and can promote the proliferation and metastasis of cancer cells." (PMID 36547079, 2022). "In line with the action and mechanism of IL-6 in vitro OSCC cells, we further determined these effects of IL-6 in the OSCC xenograft tumor." (PMID 35513871, 2022).
tumor (continued). "These mediators are responsible for the development and progression of the neoplasms; that is, PGE2 is responsible for tumor metastases, IL-6 for tumor invasion, and haptoglobin for implantation and angiogenesis." (PMID 36185863, 2022). "To further investigate changes in the tumor microenvironment, we determined the levels of TAM‐produced cyto/chemokines Ccl2, Ifnγ, Cxcl10, Cxcl9, Csf1, Csf3, and Il‐6 in the peritoneal lavage." (PMID 36221913, 2022). "We evaluated the levels of IL-6 and GM-CSF, which regulate JAK2–STAT3 activation, in serum of tumor-bearing mice after treatment with different exosomes." (PMID 35600363, 2022). "IL-6/STAT3 axis-mediated Glut5 expression enhances fructose uptake and utilization, and promotes tumor cell growth." (PMID 35813468, 2022). "TAMs promote EMT by producing factors such as IL-6, IL-8, TGF-β, as well as matrix metalloproteinase 2 and 9 which break down extracellular matrix to assist local invasion and metastasis of tumor cells." (PMID 36374927, 2022). "ICAM-1 expressed on LSECs promotes the secretion of IL-6, prostaglandin E2, VEGF and MMP2 by tumor cells, which in turn induces HSCs to secrete VEGFA and MMP2." (PMID 35965533, 2022). "IL-6 regulates the secretion of vascular endothelial growth factor (VEGF) in PC cells, thereby stimulating angiogenesis and tumor vascularization, resulting in lymphatic and distant metastasis and disease progression." (PMID 35965580, 2022). "Of particular interest is the IL‐6/JAK/STAT3 pathway, which is known to drive tumor proliferation, survival, and even metastasis." (PMID 36176603, 2022). "IL-6 seems to promote antitumor immunity mediated by a Th17 response, and IFN-γ promotes tumor antigen presentation." (PMID 36296703, 2022). "In our models with higher levels of intrinsic IL6 signaling pathways (30200 and HGS2), we observed this deleterious effect with increase in metastasis and reverting of tumor suppressive immune cell phenotype following cediranib-treatment at endpoint." (PMID 35313341, 2022). "They modulate the TNF-α signaling via direct and indirect effects on the tumor microenvironment, and they reduce the secretion of FGF-2, VEGF and IL-6 by both MM cells and BMSCs." (PMID 36362718, 2022). "However, in the early stage of tumor formation, several chemokines (IL-6, IL-8, etc.)secreted by tumor cells can transform normal fibroblasts around the tumor into CAFs, gradually forming a microenvironment suitable for malignant proliferation and metastasis of tumor cells." (PMID 35894206, 2022). "IL-6 and IL6SR are produced by various normal cells, but also tumor-infiltrating immune cells and tumor cells themselves." (PMID 34023914, 2022). "We evaluated the ex vivo number of IL-2-, IL-6-, IL-10-, IL-12-, TNF-α- and IFN-γ-producing spleen cells, since tumor growth can be affected by cytokines." (PMID 35265317, 2022). "These secreted chemokines, in turn, promote the recruitment of mast cells in the tumor microenvironment and the expression of mast cell angiogenic factors such as VEGF, TNFα, IL-6, IL-8 and FGF-2, which induce the tumor angiogenesis." (PMID 35805075, 2022). "Several tumor-derived cytokines such as TGF-β, TNF, IL-6 or IL-10 are able to prevent the maturation of DCs, the infiltration of mature DCs, the presentation of antigens and the activation of T and NK cells." (PMID 36611932, 2022). "IL-6 autocrine signaling by tumor cells enhanced the activation of the JAK-STAT3 signaling pathway, whereas the addition of neutralizing anti-IL-6 antibodies reduced tumor growth in a mouse model." (PMID 36010693, 2022). "Among the inflammatory cytokines are (IL)-1, IL-6, TNF-a, and IFN-g, which are believed to promote angiogenesis and tumor growth and survival, altering nutrient metabolism, leading to malnutrition." (PMID 35457471, 2022). "Whereas after tumor cell invasion, osteoclastogenesis is promoted by the release of osteoprotegerin (OPG) and cytokines (IL6, IL15 etc.), leading to bone destruction." (PMID 35388653, 2022).
tumor (continued). "In this study, CBFB knockdown decreased tumor burden, bone metastasis, and markers of bone metastasis, including CXCR4, Snail, CD44, OPN, Runx2, and IL-6." (PMID 35903297, 2022). "Multiple cell types in the tumour microenvironment, such as TAMs, granulocytes and fibroblasts, produce IL‐6, leading to JAK/STAT3 signalling activation in tumour cells that promotes cell proliferation, survival, invasiveness and metastasis." (PMID 35363937, 2022). "While the c-Met and IL-6 were more pronounced positive expressed in the indirect RFA group, providing the evidence of stimulation of aggressive tumor biology." (PMID 35710408, 2022). "Given the patient samples remain constant, the level of secretion of IL-6, VEGF-A, and VEGF-D must be altered in tumours treated with 1,4-dihydroxy quininib." (PMID 36698840, 2022). "When IL-6 was blocked, CD103+ DCs showed increased expression of MHCII, suggesting IL-6 affects tumor growth by indirectly suppressing the antigen presenting capability of lung DCs." (PMID 35778404, 2022). "The results demonstrated that UCMSCs-Tandab (IL-6/CD20) targeting CD20-positive DLBCL cells, evidenced by bounding to CD20-positive SU-DHL-2/4 cells, inhibit the proliferation of tumor cells by downregulating IL-6-related signaling pathway." (PMID 36104733, 2022). "More recently, swimming has been shown to attenuate tumor growth and cancer-related muscle atrophy by downregulating the expression of proinflammatory proteins including NF-κB, p-NF-κB, TNF-α, IL-1β, and IL-6." (PMID 36505042, 2022). "When assessing tumor-resident Th17 and Th22 in the 4T1-IL6-KO, Th17 was expanded, whereas Th22 was significantly reduced, consistent with other reports that IL-6 is a key cytokine determinate of both type 3 lineages." (PMID 36142210, 2022). "IL-1, IL-6, IL-11, IL-15, IL-17, IL-23, and TNF-α are representative proinflammatory cytokines promoting tumor cell differentiation, proliferation, and survival that build up the tumor microenvironment and tumor inflammation." (PMID 36438839, 2022). "Moreover, neutrophils belong to the main cytokine sources, such as interleukin 6, hepatocyte growth factor, transforming growth factor-β, interleukin 8, and matrix metalloproteinases and they are the factors which play an important role in different stages of tumour development." (PMID 35743468, 2022). "Although IDO inhibitors did not increase intratumoral CD8+ T cells in vaccinated mice, concomitant targeting of IL-6 and IDO promoted efficient induction of tumor-infiltrating DCs." (PMID 36405719, 2022). "Kim and colleagues generated CRISPR/Cas9 IL-6 knockout endothelial cells, which were co-implanted with UM-SCC-22B cells to form xenograft tumours and then implanted into mouse models." (PMID 36429126, 2022). "For instance, several soluble substances released in the TME, including IL-6, IL-10, IDO, M-CSF, transforming growth factor-β1 (TGF-β1), PGE2, and VEGF, can assist the immunosuppression of tumor-infiltrating DCs." (PMID 36703982, 2022). "In the TME, CAFs-secreted CCL2, CCL5, CCL17, IL-1, IL-6, IL-13, and IL-26 can also promote a Th2 and Th17 CD4+ polarization, at the expense of anti-tumor Th1 response." (PMID 36338519, 2022). "This view relates to the CAF secretome containing factors such as IL-10, TGFβ, IFNγ and IL-6 that are known to recruit macrophages, natural killer cells and CD3+ T lymphocytes during tumor initiation to promote an anti-tumor immune response." (PMID 36671452, 2022). "In HCC, tumor-associated macrophages (TAMs) can produce cytokines to sustain tumor growth (i.e., IL-1β, TNF, IL-6), promote neo-angiogenesis via the VEGF pathway, and induce cytokine-mediated immunosuppression (i.e., IL 10, TGF-β)." (PMID 36551635, 2022). "Relative to HCC827R‐CSC‐EVs shNC, HCC827R‐CSC‐EVs shAPE1 resulted in down‐regulated levels of APE1, IL‐6 and p‐STAT3/STAT3 in tumour tissues of Erlotinib‐treated mice (all p < .01)." (PMID 35605028, 2022).
tumor (continued). "Interleukin-6 (IL6), as a key regulator of bone remodeling, is produced by tumor cells through autocrine and paracrine mechanisms in the bone microenvironment." (PMID 35872837, 2022). "To address the role of LCN2 in the collaboration between STAT3 and NF-kB activated by IL-6, we analyzed the expression of the STAT3-mediated PI3K signaling pathway and NF-kB/STAT3 target genes related to survival, anti-apoptosis, and tumor progression." (PMID 35470375, 2022). "IL-6 promotes M2 macrophage polarization while concurrently stimulating TNBC stemness and tumor progression." (PMID 35371975, 2022). "CAFs also produce CCL2, CXCL12, IL-6, IL-10, glycoprotein CHI3L1, macrophage colony-stimulating factor to promote the migration of monocytes into tumor tissue and support their transdifferentiation into the M2 phenotype." (PMID 36324128, 2022). "In the breast, inflammation mediated by TNFA, IL6 and IL8 can favour a pro-tumorigenic environment and promote tumour initiation, growth, and progression." (PMID 35160252, 2022). "Generally speaking, cytokines dominated by IL-6 are beneficial for tumor proliferation and metastasis, while these inflammation factors mediated by IFN-γ have an anti-tumor effect on blocking tumor progression." (PMID 36004920, 2022). "ZEB1 regulates the expression of paracrine signals such as hepatocyte growth factor (HGF) and interleukin 6 (IL-6) in tumor cells and CAFs, highlighting that the ZEB1–CTGF axis plays a key role in regulating the network between tumor cells and CAFs." (PMID 35159011, 2022). "Pro-tumor/anti-inflammatory macrophages are reported to secrete excessive angiogenic cytokines such as VEGF, IL-6, IL-8, CCL-2, and MMP-9, which results in aberrant angiogenesis and the hypoxic H&N-specific TME in vitro and in vivo." (PMID 35992863, 2022). "This system is a vicious circle because TAMs are promoted by the tumor itself, which secretes various factors such as IL-6, IL-10, TGF-β, and PGE2, and in return, TAMs promote the tumor’s proliferation and survival." (PMID 35214076, 2022). "The intracellular expression of FABP4 in macrophages downregulates miR-29b via enhanced activation of NF-κB, which negatively regulates the IL-6/STAT3 signaling pathway and leads to subsequent tumor colony formation." (PMID 36060264, 2022). "IL-6 can inhibit the maturation of DCs through the STAT3 signaling pathway, attenuating anti-tumor immunity." (PMID 36119033, 2022). "The combined inhibitors of IL-6 and CTLA-4, by contrast, improve the survival of LLC1 tumor-bearing mice." (PMID 36547898, 2022). "For the first time, the correlation of salivary levels of TNF-α, IL-1β, and IL-6 with HER2 status, MCP-1, IL-1β, IL-2, and IL-4 with the hormonal status of the tumor was shown." (PMID 36286034, 2022). "Plasmacytoid DC usually promote the anti-tumor responses via the Toll-like receptor 9 (TLR9) -dependent synthesis of interferon-α (IFN-α), interleukin-6 (IL-6) and tumor necrosis factor-α (TNF-α)." (PMID 36143308, 2022). "The activated macrophages produce several inflammatory mediators, such as interleukin-6 (IL-6), interleukin-1β (IL-1β), tumor necrosis factor-α (TNF-α) and monocyte chemotactic protein-1 (MCP-1), and disturb the tumor microenvironment." (PMID 36064319, 2022). "Tumor progression can be promoted by these factors through various mechanisms, including IFNγ and IL-17 mediated tumor immune surveillance or the recruitment of immune cells into the tumor microenvironment via TNF-α, IL-1β, and IL-6." (PMID 36012113, 2022). "M1 macrophages release proinflammatory cytokines such as IL-1β, IL-6, and TNF-α to activate innate immunity and kill tumor cells." (PMID 35210436, 2022).